INS (insulin)
Diseases named in the same sentence as INS in open-access papers (continued):
Sharing a sentence is not in itself a finding about the gene and the disease.
diabetes (continued). "The pregnancy state is already defined as a condition of predisposition to diabetes, due to the production of placental enzymes (which act in the degradation of insulin), and hyperglycemic hormones." (PMID 35195193, 2022). "We found evidence of a positive association with fasting insulin, 2-h insulin, incident diabetes and IL-6—with overall medium study quality." (PMID 35544519, 2022). "For example, medications for the treatment of diabetes such as Metformin were negatively associated with mortality among diabetic patient while exogenous insulin use and Sulfonylureas were associated with an increased risk for cancer mortality." (PMID 35921366, 2022). "High linoleic acid levels are associated with reduced risk in type 2 diabetes mellitus, improved insulin sensitivity, and reduced inflammation." (PMID 35269531, 2022). "Intriguingly, insulin use has been identified as a risk factor in COVID‐19‐positive, patients with diabetes." (PMID 35441801, 2022). "In diabetes, the effects of insulin exposure are sometimes considered a risk factor for lung cancer; however, the effects are not consistent in men and women." (PMID 35648377, 2022). "Lack of staff and time for patient education are common causes for delayed insulin treatment and for low education among diabetes patients." (PMID 36554673, 2022). "It is known to have insulin sensitizing, anti-atherogenic and anti-inflammatory properties, and hypoadiponectemia is associated with obesity, insulin-resistance and type 2 diabetes mellitus (T2DM)." (PMID 35872989, 2022). "In fact, no causal relationship has been highlighted between genetic instruments for metabolic traits [e.g. insulin resistance, BMI, or diabetes] and SCZ risk." (PMID 36354137, 2022). "Individuals with metabolically NWO, first described in the late 1990s, have been noted to be insulin resistant and predisposed to type 2 diabetes mellitus, hypertriglyceridemia, and premature coronary heart disease." (PMID 36185692, 2022). "The Professional Committee of Gestational Diabetes of the China Maternal and Child Health Association recommended insulin as the first-line hypoglycemic therapy for women with GDM based on the recommendations of the American Diabetes Association." (PMID 36530712, 2022). "Insulin sensitivity seems to improve and the risk of diabetes gradually decreases after smoking cessation." (PMID 36293800, 2022). "Diabetes mellitus (DM) is a feature of a metabolic disease caused by elevated blood glucose levels due to insufficient insulin secretion or action, or both." (PMID 35215420, 2022). "Obesity or abdominal obesity often coexists with diabetes as they are linked with defective insulin secretion and insulin resistance." (PMID 34738737, 2022). "They secrete their metabolites into the blood, thus affecting the host’s overall metabolism and causing insulin secretion disorder, insulin resistance, and obesity, prerequisites for the development of diabetes." (PMID 36397429, 2022). "Diabetes is associated with excessive production of reactive oxygen species (ROS), leading to oxidative damage in the liver and defects in insulin action and secretion." (PMID 36613249, 2022). "The exact mechanism explaining the role of Mg in the pathogenesis of diabetes is not fully understood, although there are some pathways linking Mg deficiency and disturbances in glucose and insulin metabolism." (PMID 35565682, 2022). "Diabetes mellitus (DM) is a chronic condition associated with raised levels of blood glucose due to the body cannot produce any or enough of the hormone insulin or cannot effectively utilize the produced insulin by the body." (PMID 35895700, 2022). "One of the main mechanisms through which statins cause diabetes mellitus is by increasing insulin resistance in peripheral tissues." (PMID 35892446, 2022). "Both organs are associated with the pancreas which controls insulin production and the development of diabetes mellitus." (PMID 36465856, 2022).
diabetes (continued). "Diabetes mellitus is a metabolic condition characterized predominantly by chronic hyperglycemia, which is caused from insulin resistance or from impairment of insulin secretion." (PMID 35625786, 2022). "Only those with the Gly288fs* variant were diagnosed with diabetes before the follow-up period and received insulin treatment." (PMID 35299962, 2022). "Expression data were related to islet phenotypes, diabetes status, other islet-expressed genes, islet hormone-encoding genes and for expression in insulin target tissues." (PMID 35948367, 2022). "Insulin clearance is relatively lower in ethnic groups at high risk for diabetes such as African Americans and Hispanic Americans, compared to European Americans." (PMID 35163746, 2022). "The objective of this pilot study was to characterize the gastrointestinal microbiome of dogs with diabetes mellitus at the time of diagnosis and over the first 12 weeks of insulin therapy and identify associations with glycemic control." (PMID 36067170, 2022). "Insulin treatment is another typical issue associated with weight gain and diabetes, and it has a considerable pathophysiological impact on various phases of the disease." (PMID 35197747, 2022). "This remarkably reshapes the traditional notion that hyperglycemia associated with diabetes results exclusively from impaired pancreatic islet function (e.g., insulin secretion and/or resistance) in the STZ animal model." (PMID 35619170, 2022). "Islets are primarily comprised of insulin-secreting ß cells and interestingly mice that are null for CDK4 expression develop insulin-deficient diabetes." (PMID 36051751, 2022). "It is well-known that miR-29a is associated with insulin secretion in pancreatic β-cells, and prevents the progression of diabetes during ER dysfunction of the β-cells." (PMID 35655590, 2022). "Herein, a more direct measure of excess adiposity compared to BMI and longer diabetes duration provided a critical tool to examine associations between the insulin regimen and adiposity in this large cohort setting." (PMID 35127949, 2022). "Since T1DM is known as ‘fragile diabetes’, absolute insulin deficiency and lifelong insulin-dependent treatment render great glucose fluctuations and frequent hypoglycemia in this population." (PMID 36204110, 2022). "Diabetes is a chronic disease caused by an imbalance of insulin release to the bloodstream in response to excessive glucose influx, which causes hyperglycemia." (PMID 36518402, 2022). "Impaired autophagy will further aggravate the metabolic disorder associated with diabetes in insulin target tissues (such as liver, skeletal muscle, and adipose tissue) and pancreatic β cells." (PMID 35252293, 2022). "Diabetes mellitus (DM) is one of the most prevalent metabolism-related disorders associated with impaired insulin production (type 1) or developed insulin resistance (type 2)." (PMID 36558434, 2022). "Hyperglycemia is caused by the insufficiency of insulin production due to the pancreas (type 1 diabetes mellitus (T1DM)) or insulin resistance (type 2 diabetes mellitus (T2DM))." (PMID 36430714, 2022). "The cause of diabetes is both a dysfunction in insulin secretion by the beta cells of the pancreas and a disturbance in insulin action in tissues leading to insulin resistance." (PMID 36232910, 2022). "For those who contracted COVID-19, high blood glucose levels caused by the infection were met with efforts to titrate insulin doses, and informants called the diabetes nurse for support and advice on this matter." (PMID 35393314, 2022). "T2DM, accounting for 85% of the diabetes burden, is caused by insulin resistance and inadequate compensatory insulin secretion, which is associated with several lifestyle factors, such as age, obesity, and pregnancy." (PMID 36555531, 2022).
diabetes (continued). "Disorders in insulin production or insulin sensitivity and function cause one of the major chronic metabolic diseases, diabetes mellitus, characterized by a dysfunction in the balance of glucose homeostasis." (PMID 35237285, 2022). "Type 2 diabetes represents over 90% of diabetes and is associated with reduced sensitivity to insulin by peripheral tissues." (PMID 35563963, 2022). "Type 2 diabetes mellitus (T2DM) is a chronic endocrine disorder due to the reduction of insulin sensitivity and relative deficiency of insulin secretion." (PMID 36444166, 2022). "Type 1 diabetes mellitus (T1DM) is a chronic autoimmune disease with absolute deficiency of insulin secretion as the main manifestation, with a significant genetic predisposition and autoimmune destruction." (PMID 35242879, 2022). "Diabetes is a chronic disease, which is caused by the inability of the body to produce enough insulin or the inability to use insulin properly." (PMID 36292657, 2022). "In this report, we present a case of a 46-year-old patient with insulin-dependent diabetes mellitus (IDDM) who avoided insulin treatment due to associated peripheral edema." (PMID 36017419, 2022). "Diabetes mellitus is a carbohydrate metabolic disorder caused by decreased insulin production or increasing insulin resistance." (PMID 36297746, 2022). "In association with insulin therapy, diet treatment is an integral part of diabetes management as it is able to influence glucose control, as also demonstrated in such a study." (PMID 36562032, 2022). "In EPICOM, we reported offspring born to women with T1D to have an increased risk of pre‐diabetes, higher BMI, reduced insulin sensitivity and relative insulin secretion deficiency." (PMID 34800010, 2022). "In conclusion, the DOP/PEI-PBA hydrogel is expected to be used as an ideal controlled release carrier for insulin for the clinical treatment of diabetes patients with insulin deficiency." (PMID 36012342, 2022). "All patients met the diagnostic criteria for T1DM with diabetes symptoms, blood glucose ≥ 11.1 mmol/L, and low insulin and C-peptide levels." (PMID 36460989, 2022). "The direct cause of diabetes is the dysfunction of islet cells or the insensitivity of the body to insulin, which leads to the decrease of insulin secretion, and the low efficiency of glucose utilization and storage in the blood." (PMID 35630690, 2022). "T2D is characterized by insulin resistance, disturbances in the insulin secretion and progressive loss of 25-50% of pancreatic beta cells in the course of diabetes." (PMID 36246880, 2022). "Diabetes mellitus is characterized by chronic hyperglycaemia and impaired carbohydrate, lipid and protein metabolism caused by complete or partial insufficiency of insulin secretion and/or insulin action." (PMID 35179802, 2022). "Mechanistic insights suggest that ectopic liver fat is probably part of the pathogenic process in diabetes, contributing to hepatic insulin resistance, excess gluconeogenesis, and higher fasting glucose levels." (PMID 36013008, 2022). "Rodent studies can still be used to infer metabolic consequences of long-term dioxin exposure; our review suggests that TCDD decreases insulin secretion and increases susceptibility to hyperglycemia and diabetes, at least in females." (PMID 35156417, 2022). "In physiological and biochemical indicators, high SBP, FPG, HbA1c, insulin, TG, and uric acid were significant factors affecting high risk for adolescent diabetes." (PMID 36010139, 2022). "The gradual impairment of insulin secretion and insulin signaling in diabetes is associated with elevated NEFA and increased myocardial free fatty acid uptake, accumulation of diacylglycerol, and protein kinase C activation." (PMID 35453469, 2022). "Studies have also shown that short-chain fatty acids (SCFAs) are closely related to diabetes in that they improve insulin resistance and pancreatic damage while attenuating the inflammatory responses caused by diabetes." (PMID 35571895, 2022).
diabetes (continued). "Multiple mechanisms are involved in impaired insulin secretion associated with diabetes mellitus due to either dysfunction or loss of pancreatic β-cells." (PMID 35397560, 2022). "Decades of unequivocal evidence suggest that waist circumference provides both independent and additive information to BMI for predicting diabetes risk, and decreased waist circumference is closely associated with better insulin sensitivity." (PMID 35773443, 2022). "Because of their potential to alleviate insulin resistance and minimize the risk of hypoglycemia, insulin sensitizers represent a complementary therapeutic approach for diabetes." (PMID 35502441, 2022). "We apply ricu to first study the association of lactate and mortality and then study the association of insulin dosage and diabetes." (PMID 37318234, 2022). "Diabetes mellitus is a chronic endocrine disorder and metabolic disorder caused by insufficient insulin secretion, functional defects, and insulin resistance due to lifestyle changes or genetic factors." (PMID 35383532, 2022). "As an approach to β-cell replacement therapy, pancreatic islet transplantation has shown promise as a therapy for insulin-deficient diabetes and it contributes to the reconstruction of glucose homeostasis." (PMID 35409105, 2022). "Diabetes mellitus is a chronic metabolic disease characterized by hyperglycemia caused by defects in insulin secretion, insulin function, or both." (PMID 35418054, 2022). "Diabetes Mellitus and its complications are primarily caused by insulin resistance and impaired insulin signaling." (PMID 36092798, 2022). "The activity of islet cells is closely associated with diabetes, and insufficient insulin secretion caused by pancreatic β-cell failure contributes to hyperglycemia." (PMID 35422764, 2022). "The decrease in hypertrophy of epididymal fat pads enhances insulin sensitivity which is one of the key factors for treating obesity and associated diabetes mellitus." (PMID 36033946, 2022). "Through hyperglycemia, hyperlipidemia, and associated complications, diabetes induces oxidative stress that can result in mitochondrial dysfunction, insulin resistance as well as lipid, protein, and DNA breakdown and cause damage to multiple organs." (PMID 36531176, 2022). "Diabetes mellitus (DM), of any type, is a severe metabolic disease characterized by high blood glucose caused by insulin production defects or inefficient insulin utilization." (PMID 36364880, 2022). "Oxidative stress reduces insulin secretion by damaging the mitochondria of pancreatic beta cells and causes diabetes." (PMID 36407541, 2022). "Diabetes mellitus (DM) is a metabolic disorder associated with either the failure of the pancreatic islet beta cells that produce insulin, or insulin resistant where the human body cannot uptake the available insulin effectively." (PMID 35081168, 2022). "We assessed the polygenic risk score for type 2 diabetes, age at onset of diabetes and measures of body composition, as well as plasma glucose, serum insulin, proinsulin, C-peptide, glucagon and NEFA response during the OGTT." (PMID 34951657, 2022). "In fact, an imbalance in ROS generation affects insulin secretion and sensitivity, which causes diabetes." (PMID 35655590, 2022). "Diabetes is a metabolic disorder characterized by hyperglycemia caused by deficiency of insulin secretion and/or deficiency of insulin action." (PMID 36618372, 2022). "Diabetes is caused by hyperglycemia caused by deficiency of insulin secretion or dysfunction of islet secretion." (PMID 36003336, 2022). "Diabetes is a group of metabolic diseases characterized by hyperglycemia caused by the direct or indirect deficiency of insulin." (PMID 35008906, 2022). "Type 2 diabetes mellitus (T2DM) is a common type of diabetes disease caused by insufficient insulin action to insulin-sensitive tissues (insulin resistance), which leads to dysfunction of beta-pancreatic cells to produce insulin and high blood glucose levels." (PMID 35807241, 2022).
diabetes (continued). "Numerous pathogenic mechanisms are involved in the onset of diabetes, ranging from autoimmune destruction of the pancreatic β-cells with consequent insulin deficiency to abnormalities that result in resistance to insulin action." (PMID 35480484, 2022). "Diabetic hyperglycemia is caused by defective biological effects of insulin (type 2 diabetes mellitus) resulting from obesity or decreased insulin secretion (type 1 diabetes mellitus)." (PMID 36005597, 2022). "Characterized by total GCK deficiency, MODY2 patients with compound heterozygous loss-of-function mutations display permanent insulin-requiring diabetes mellitus (PNDM) with neonatal onset." (PMID 36361703, 2022). "Type 1 diabetes mellitus (T1D) has been generally characterized as a condition with an insulin-deficient phenotype." (PMID 35703516, 2022). "It is known that a loss of function mutation in Slc30a8 has a protective effect against diabetes, by enhancing insulin secretion." (PMID 35784893, 2022). "The pathogenesis of insulin resistance and diabetes has been associated with reduced fatty acid β-oxidation inducing lipotoxicity and impaired insulin signaling." (PMID 36145136, 2022). "eFigure 3 in the Supplement summarizes the association of diabetes with the distal outcomes when stratified by insulin and oral medication use." (PMID 36178688, 2022). "On the other hand, RBPs and miRNAs implicated in diabetes have been shown to affect the expression of key components of insulin pathway, such as INSR and IRS." (PMID 35204710, 2022). "Diabetes mellitus (DM), a metabolic disorder characterized by hyperglycemia induced by insulin secretion deficiency and/or resistance to its action, affects millions of people around the world." (PMID 35684319, 2022). "Lipids secreted from obese adipose tissue are accumulated in peripheral tissues such as the liver, pancreas, and muscle, and impair insulin sensitivity causing type 2 diabetes mellitus (T2DM)." (PMID 36209391, 2022). "Diabetes accelerates muscle catabolism via insulin resistance and attenuating insulin signaling, causing rapidly loss of muscle mass and strength." (PMID 35711555, 2022). "Although challenging, weight loss increases insulin sensitivity and reduces the risk of developing insulin resistance and diabetes." (PMID 35267895, 2022). "Diabetes mellitus (diabetes) is a chronic metabolic disease characterized by high blood glucose levels and associated with impaired insulin secretion, insulin action, or both." (PMID 36589234, 2022). "In the current study, diabetes was induced by feeding mice with a high-fat diet and carbohydrates resulting in increased plasma insulin levels causing glucose intolerance and insulin resistance." (PMID 36875821, 2022). "Insulin is administered subcutaneously to the patients with diabetes mellitus who have insulin deficiency." (PMID 36452220, 2022). "These authors showed that the activation of SREBP2 in these cells can cause diabetes by a mechanism involving the loss of β-cells and insulin secretion." (PMID 35625914, 2022). "Plasma ceramides and sphingomyelins have been independently linked to diabetes risk, glucose and insulin levels, and the risk of several cardiovascular (CVD) outcomes." (PMID 36042511, 2022). "The metabolic disorders related to type 1 diabetes mellitus are a result of deficiency of insulin secretion caused by the immune destruction of islets of Langerhans of the pancreas." (PMID 35282429, 2022). "There is a relative paucity of literature regarding DMG, although lower concentrations have previously been associated with higher blood glucose, increased insulin resistance, and an increased risk of incident diabetes." (PMID 34240265, 2022). "Diabetes mellitus is a chronic condition in which decreased insulin activity, manifested as either tissue insulin insensitivity or insulin amount, causes reduced glucose disposal." (PMID 36012137, 2022).